PRLR (prolactin receptor)
Diseases named in the same sentence as PRLR in open-access papers (continued):
Sharing a sentence is not in itself a finding about the gene and the disease.
breast cancer (continued). "On the other hand, a study using breast cancer cell lines identified GSK3β as a kinase of the prolactin receptor at Ser349; this phosphorylation site labels the prolactin receptor for degradation." (PMID 29643836, 2018). "PRLr is relatively abundant in human breast cancer, potentially due to decreased phosphorylation of Ser349." (PMID 29102676, 2018). "PrLr is commonly stabilized in human breast cancer and NRF2 levels are elevated in several neoplastic diseases, most notably in non-small cell lung carcinoma (NSCLC) and lung squamous carcinoma." (PMID 29102676, 2018). "Meanwhile progressive inactivation of GSK3 β correlates with elevated levels of PRLr protein in human breast cancer tissue." (PMID 29102676, 2018). "PRLR is well known to play an important role in the physiology of the human breast and in the etiology, progression breast cancer." (PMID 28423697, 2017). "These in turn recruit coactivators and through epigenetic changes favor the recruitment of TFIIB, and Pol II for transcriptional induced expression of PRLR gene by E2 in MCF-7 breast cancer cells." (PMID 28423697, 2017). "Extensive in vitro studies of human breast cancer cells have shown that the PRLR, like other cytokine receptors, can activate multiple signaling pathways." (PMID 28103936, 2017). "In this study we demonstrated the requirement of the participation of PRL/PRLR in transcriptional upregulation/expression of the PRLR induced by E2/ERα in breast cancer cells." (PMID 28423697, 2017). "In previous studies we determined that endogenous PRL which is present in breast cancer cells contributes to basal levels of PRLR expression in MCF-7 and T47D cells and these were magnified by addition of exogenous PRL." (PMID 28423697, 2017). "Such cross-talk activation of ERBB2/HER2 signalling was identified as an alternate route in the upregulation of PRLR induced by its cognate hormone in breast cancer cells." (PMID 27564112, 2016). "Nevertheless, other hormone receptors such as prolactin receptor (PRLR) or growth hormone receptor (GHR) have been evaluated in human breast cancer." (PMID 27649560, 2016). "Increased levels of PRLR in breast cancer indicate their participation in the proliferation of breast tumor and cancer cells induced by prolactin." (PMID 27564112, 2016). "To date we have found three modalities for PRLR up-regulation at the transcriptional level with consequent increases in the expression of a functional PRLR in breast cancer cells." (PMID 27564112, 2016). "Short forms of the PRLR S1a and S1b with abbreviated cytoplasmic domain generated by alternative splicing were also found in normal, breast cancer tissues and cells." (PMID 27564112, 2016). "PRL and the PRLR enhanced the endogenous capacity of the breast cancer cells to directly induce the differentiation of osteoclasts via production of soluble factors and also contributed to their osteolytic ability." (PMID 27782069, 2016). "We recently discovered that breast cancer cells that migrated to the bone carry the PRL-receptor (PRLR) and that PRL signaling to breast cancer cells advances osteolytic osteoclast differentiation via the production of a soluble factor that modulates the bone." (PMID 27782069, 2016). "Osteoclasts do not express the PRLR, so any effect of PRL on osteoclasts would be indirect, including via PRLR+ osteoblasts or PRLR+ breast cancer cells." (PMID 27782069, 2016). "Our results indicate that while PRLR expression is down regulated in TNBC in comparison to other breast cancer molecular subtypes, intermediate/high PRLR mRNA levels are still preserved in ~30% of TNBC cases." (PMID 27480353, 2016). "The PRLR has been found in the vast majority of human breast cancers and PRL signaling has been implicated in breast cancer cell proliferation, survival, motility and angiogenesis." (PMID 27542844, 2016).
breast cancer (continued). "This cooperation, which was prevented by matrices of normal physiological stiffness, underscores the potent synergy of these factors in ERα+/PRLR+ breast cancer." (PMID 25607819, 2015). "Although interactions between the ECM and PRL/PRLR signals in breast cancer have been examined, the current studies revealed striking effects of the combination of PRL and estrogen in a high density/ stiff ECM that were not apparent with either hormone alone." (PMID 25607819, 2015). "On these grounds, PRLR is currently being exploited as a potential therapeutic target in breast cancer." (PMID 26733941, 2015). "PRLR mRNA expression was significantly lower in both benign and malignant mammary neoplasms than in normal tissues (p = 0.009 and p < 0.001, respectively) with lowest values detected in the malignant group." (PMID 26370564, 2015). "In summary, we have shown that high density/ stiff collagen matrices enhance pro-tumorigenic crosstalk between estrogen and PRL in ERα+/PRLR+ luminal breast cancer cells." (PMID 25607819, 2015). "Steroid levels were not influenced by their corresponding receptor expression in mammary neoplasms, but increased PRL levels were negatively associated with low PRLR gene expression in malignant tumors." (PMID 26370564, 2015). "High circulating PRL is a risk factor for metastatic ERα+ breast cancer, and its cognate receptor (PRLR) is expressed in most breast cancers, especially those expressing ERα." (PMID 25607819, 2015). "T47D and MCF-7 cells are two of the most studied ERα+/PRLR+ luminal breast cancer cell lines with respect to both estrogen and PRL actions." (PMID 25607819, 2015). "Here we examined the effect of matrix density on 17β-estradiol (E2) activity and PRL/E2 interactions in two well-characterized, ERα+, PRLR+, luminal breast cancer cell lines cultured in defined 3D compliant and stiff collagen-I matrices." (PMID 25607819, 2015). "In the same context, PRL/PRLR signaling has the ability to promote progression and invasion in breast cancer through independent pathways to JAK2/STAT5, such as c-Src, FAK and MAPK." (PMID 26346346, 2015). "This demonstrates the relevance of the endogenous levels of PRL in the up-regulation of PRLR observed in mammary tumors." (PMID 25193864, 2014). "Our studies have shown that prolactin produced in breast cancer cells through intracrine activation of PRLR and via at least two signal transduction pathways, JAK2/STAT5 and JAK2/PI3K/MEK/ERK, up-regulates the human prolactin receptor." (PMID 25193864, 2014). "The present study supports the novel pathophysiological concept that extracellular acidosis within the microenvironment of breast cancer potently and selectively disrupts prolactin receptor signaling, including Stat5 activation." (PMID 24004716, 2013). "Differently than breast cancer cells, in cervical cancer cell lines HeLa, SiHa and C-33A we detected three of the PRLR forms (110 kDa, 60 kDa and 50 kDa)." (PMID 24148306, 2013). "Studies are warranted to determine how extracellular tumor acidosis impacts pharmacological strategies centered on targeting prolactin receptor pathways in breast cancer and potentially other malignancies." (PMID 24004716, 2013). "In most studies evaluating human breast cancer, PRLR expression level in malignant tumors was equal or decreased compared to benign lesions and normal tissue." (PMID 22647582, 2012). "In breast cancer cells, inhibition of GSK3β through serine phosphorylation on residue 9 has been shown to correlate with elevated PRLr levels." (PMID 22606260, 2012). "In summary, results of our preliminary study show that PRLR are expressed in canine mammary tumors, and expression seems to decrease with increasing malignancy." (PMID 22647582, 2012). "In comparison with other tissues and breast cancer cells, high levels of prolactin receptor gene (PRLR) transcripts were demonstrated in parathyroid tissues." (PMID 22606260, 2012).
breast cancer (continued). "In breast cancer cell culture models, PRLR expression was found to be increased, decreased or unaltered compared to normal breast epithelium, depending on the cell line used." (PMID 22647582, 2012). "The expression was compared with two cell lines frequently used as models for PRLr signalling in breast cancer: T47D and MCF-7 which are both known to express very high or high PRLr levels, respectively." (PMID 22606260, 2012). "Sporadic publications proposed a tumor-promoting role, and presence of PRLR was documented in canine mammary tumor cells in vivo and in vitro." (PMID 22647582, 2012). "In gynecomastia, PRLR expression was mainly seen along luminal cell borders, while in mammary carcinomas from males signals were mostly cytoplasmatic." (PMID 22647582, 2012). "We genotyped 8 PRL and 20 PRLR tag SNPs in 1965 breast cancer cases and 2229 matched controls, aged 20-74, and living in Warsaw or Łódź, Poland." (PMID 21470416, 2011). "To characterize PRLR isoforms in breast cancer we performed qPCR on 7 ductal and 7 lobular carcinoma specimens selected at random from samples that were also immunostained using our isoform specific antibodies." (PMID 21144038, 2010). "We have prepared and characterized polyclonal antibodies against each of the human PRLR isoforms that can effectively be used to characterize human breast cancers." (PMID 21144038, 2010). "Differences in PRLR isoform expression levels were observed and quantified using histosections from xenografts of established human breast cancer cells lines, and ductal and lobular carcinoma human biopsy specimens." (PMID 21144038, 2010). "With the discovery of the various isoforms of the PRLR, a more detailed analysis of the cellular localization of the receptor as well as possible differences between subtypes of breast cancer was warranted." (PMID 21144038, 2010). "Approaches to antagonise autocrine prolactin in breast cancer cell lines have centred on prolactin-neutralising antibodies and PRLR antagonists." (PMID 18681966, 2008). "Using this and other antibodies, researchers have identified PRLR expression to some degree in most human breast cancers and normal breast tissue, on the luminal surface." (PMID 21655368, 2008). "We examined the effects of the 'pure' prolactin receptor antagonist Δ1–9-G129R-hPrl (Δ1–9) on the breast cancer cell number and clonogenicity, alone and in combination with chemotherapy." (PMID 18681966, 2008). "In the current study we examined the effects of the 'pure' prolactin receptor antagonist Δ1–9 in breast cancer models in vitro." (PMID 18681966, 2008). "We sequenced the exons and splice-site regions of PRL and PRLR in germline DNA from 95 advanced breast cancer cases (19 of each racial/ethnic group)." (PMID 18053149, 2007). "We sequenced the coding regions of PRL and PRLR in 95 advanced breast cancer cases (19 of each racial/ethnic group) to uncover putative functional variation." (PMID 18053149, 2007). "We evaluated genetic variation in the PRL and PRL receptor (PRLR) genes as predictors of plasma PRL levels and breast cancer risk among African-American, Native Hawaiian, Japanese-American, Latina, and White women in the Multiethnic Cohort Study (MEC)." (PMID 18053149, 2007). "We studied expression of prolactin receptor mRNA in human breast cancer cell lines MCF-7, SKBR-3, T47D and BT-20 treated with and without retinoids using Northern blot and a quantitative polymerase chain reaction (PCR) method." (PMID 9888458, 1999). "The correlation between prolactin (PRLR) and oestrogen (ER) or progesterone receptors (PgR) in breast cancer and a possible prognostic significance of PRLR at 10 year follow-up have been investigated in the Naples (GUN) adjuvant trial." (PMID 2223582, 1990). "A promising avenue of future studies could involve the relationship between PRLR genotypes, protein levels, tumor subtypes, and types of breast cancer events." (PMID 40723262, 2025).
breast cancer (continued). "Additionally, direct CRISPR/Cas9 knockout of the PRLR in HR+ and HER2-E breast cancer cells caused dedifferentiation/aberrant differentiation, loss of linage specificity and led to enhanced tumorigenic and metastatic phenotypes." (PMID 40157909, 2025). "Importantly, blocking PRLR expression in HR+ breast cancer MCF7 cells resulted in luminal-basal conversion with increased expression of mesenchymal-stem-like, tumorigenic and metastatic features as well as resistance to therapy." (PMID 40157909, 2025). "Similarly, PRLR gene expression is highest in differentiated HR+/luminal A breast cancer subtype and least expressed in the triple negative, basal-like subtype and its expression correlates with favorable prognosis." (PMID 40157909, 2025). "This research showed that tamoxifen upregulates PRLR in breast cancer cells, leading to resistance." (PMID 40978029, 2025). "Moreover, the potential role of PRLR inhibition as a therapeutic strategy for breast cancer warrants further exploration." (PMID 40723262, 2025). "Therefore, targeting PRL/PRLR pathway as a therapeutic avenue in breast cancer has been a topic of interest for decades." (PMID 40157909, 2025). "Importantly, stiff‐collagen ECM is known to enhance tumor growth in response to E2 and prolactin, which means that a dense matrix mediates ERα‐46 and prolactin receptor (PRLR) crosstalk to promote breast cancer progression." (PMID 39285617, 2025). "On the basis of the observation that, in several immunohistochemical studies of patients with breast carcinoma, PRLr is expressed at high levels, the evaluation of PRLr expression should be considered in these patients and should be mandatory in patients diagnosed with PRL-secreting PitNETs." (PMID 40160874, 2025). "PRLR pathway activated by PRL could significantly decrease sensitivity of ERα-positive breast cancer cells to tamoxifen." (PMID 38898487, 2024). "Our study provides a new perspective for targeting PRLR to treat breast cancer." (PMID 38898487, 2024). "Tamoxifen treatment upregulated transcription of PRLR and could induce significant accumulation of PRLR protein in breast cancer cells by alkalizing lysosomes." (PMID 38898487, 2024). "Tamoxifen up-regulates PRLR protein level in breast cancer cells and activation of PRLR pathway by PRL could decrease drug-sensitivity of breast cancer cells to tamoxifen." (PMID 38898487, 2024). "N8-PE24 could inhibit cell growth of the breast cancers and promote drug sensitivity of PRLR-positive breast cancer cells to tamoxifen and paclitaxel." (PMID 38898487, 2024). "The immunotoxin targeting PRLR could reverse drug-sensitivity to tamoxifen in tamoxifen-resistant breast cancer in vitro and in vivo." (PMID 38898487, 2024). "Signals downstream of prolactin receptor (PRLR) could synergize with ERα in breast cancer progression." (PMID 38898487, 2024). "Among postmenopausal women, plasma prolactin levels were positively associated with breast cancer risk irrespective of PRLR, pSTAT5, or pJAK2 expression (all p-heterogeneity ≥ 0.21)." (PMID 36882838, 2023). "It has also been revealed that EGF/EGFR could phosphorylate ER (ser118 and 167) and initiate downstream MAPK signaling in breast cancer cells, as well as STAT5b and PRLR transcription." (PMID 37415164, 2023). "Alternatively, this could indicate pSTAT5 is being activated in premenopausal breast cancer through a mechanism other than PRLR, which should be explored in future research." (PMID 36882838, 2023). "Although pSTAT5 can be activated through the PRLR pathway, we did not see the same increased risk of a PRLR positive breast cancer with elevated prolactin." (PMID 36882838, 2023). "It has been reported that PRLR might affect the prognosis of breast cancer by inhibiting the expression of immune checkpoints." (PMID 37600770, 2023).
breast cancer (continued). "The stabilization of PRLR is also mediated by the human epidermal growth factor receptor 2 (HER2)-/RAS-signaling-induced inhibitory phosphorylation of GSK3β in breast cancer cells, and elevated PRLR levels are correlated with GSK3β inactivation in breast cancer specimens." (PMID 37686524, 2023). "However, more studies are needed to understand the role of PRLR and prolactin in canine mammary tumors, including their protein expression levels among the subtypes and subgroups." (PMID 37789381, 2023). "PRL/PRLR is expressed in 95% of mammary tumors and 60% of male breast carcinomas." (PMID 36187116, 2022). "Our studies may provide insights for therapeutic approaches that will mitigate the transcription/expression of PRLR and its participation in breast cancer progression fueled by E2 and PRL via their cognate receptors." (PMID 36187116, 2022). "Therefore, in this era of precision medicine, we conclude that combination therapy involving pathway-selective kinase inhibitors and PRLR inhibitors depending on the status of the breast cancer can provide better outcomes in clinical studies." (PMID 36187116, 2022). "Much of the discussion revolves around the extent of PRLR expression by the tumor parenchyma, including which breast cancer subtypes and which PRLR isoforms, and importantly, whether PRL fuels tumor aggression or fosters a more differentiated phenotype." (PMID 35784527, 2022). "Collectively, in breast cancer accumulating data implies PRL/PRLR as a clinically relevant potent differentiation pathway limiting the tumorigenic phenotype and thus may serve as a potential pro-differentiation therapeutic candidate." (PMID 36157462, 2022). "Similarly, JAK1 is activated by PRLR signaling in a subset of breast cancers, while underexpression of JAK1 is needed for the invasion of immune response." (PMID 35620468, 2022). "PRLR has been reported to promote cell proliferation and inhibit apoptosis in breast cancer." (PMID 35309064, 2022). "In addition to the role of the predominant LF of PRLR in breast cancer, a recent study showed that the human intermediate PRLR (alternatively spliced isoform) is a mammary proto-oncogene capable of stimulating cell survival and proliferation." (PMID 36187116, 2022). "Also, among the different breast cancer subtypes, PRLR mRNA levels were highest in luminal A subtype and least expression was detected in the most aggressive TNBC basal-like subtype." (PMID 36157462, 2022). "Moreover, recent studies have shown a relation between a newly discovered prolactin receptor type, the human prolactin receptor intermediate isoform (hPRLrI), and breast cancer development." (PMID 35327605, 2022). "Interestingly, reports have shown that expression of truncated forms of the PRLR long form resulted in initiation of mammary tumorigenesis in mouse models of ER+ breast cancer as well as in human MCF10A xenograft model." (PMID 36157462, 2022). "Collectively, these data suggest that the REGN2878-DM1 antibody-drug conjugate has potential to target PRLR and may have implications in the treatment of breast cancer with high expression of PRLR." (PMID 36714582, 2022). "This evidence describes an indirect way oestradiol could upregulate CPTI and enhance FA oxidation in breast cancer through the ER-PRLR crosstalk and direct upregulation of the PRLR pathway by oestradiol." (PMID 35448537, 2022). "In this review, we provide an overview of the current understanding of the transcriptional regulation of PRLR and signal transduction in physiological and pathological modalities in mammary glands with special emphasis on the role of PRL/PRLR signaling in breast cancer." (PMID 36187116, 2022). "Targeting both the tumor antigen PRLR and the T cell surface CD3 antigen could recruit and activate T cells to kill PRLR expressing breast cancer cells." (PMID 35739271, 2022).